CD81 (CD81 molecule)
Diseases named in the same sentence as CD81 in open-access papers (continued):
Sharing a sentence is not in itself a finding about the gene and the disease.
glioblastoma (17 papers, 2012 to 2025). The most malignant astrocytic tumor (WHO grade IV). "The expression of the tetraspanin CD9, responsible for the maintenance of glioblastoma-like stem cells, and of CD81, associated with enhanced resistance to radiotherapy, is increased in low-grade gliomas and glioblastoma, respectively." (PMID 39684236, 2024). "We selected CD81—one of the two genes independently associated with overall survival in glioblastoma patients according to the Gene Expression Profiling Interactive Analysis (GEPIA) server —for subsequent functional validation (the P of CD81 is smaller)." (PMID 35936722, 2022). "Another study has also shown that HSP70 inhibits brain tumor development in a C6 glioblastoma mouse model, which is associated with NK cell and T lymphocyte killing abilities of glioblastoma, as well as increased activities of NK cells and CD81+ T lymphocytes." (PMID 32631421, 2020). "Immunostaining is accomplished with fluorescent antibodies against EV markers such as CD9, CD63, and CD81 or cancer markers, in this particular study from three glioblastoma cell lines overexpressing EGFRvIII, EGFR, or IDH1‐R132." (PMID 35898167, 2023). "After irradiation, however, the amount of CD9 and CD81-positive EVs increased in supernatant when glioblastoma cells underwent cell death, particularly apoptosis." (PMID 36203458, 2022). "We concluded that the amount of secreted CD9 and CD81-positive EVs correlated with cell death induction in glioblastoma cells 72 h after irradiation." (PMID 36203458, 2022). "Finally, CD81 may serve as a diagnostic and prognostic biomarker in glioblastoma." (PMID 35936722, 2022). "We observed that interfering with CD81 expression inhibited proliferation, migration, and invasion and promoted apoptosis in U251 and U118 glioblastoma cells in vitro, suggesting a potential role of CD81 in glioblastoma diagnosis and prognosis." (PMID 35936722, 2022). "Next, we employed flow cytometry to analyze CD9 and CD81 protein levels in cells of the four glioblastoma cell lines." (PMID 36203458, 2022). "Analyzing data accessible at the GEPIA platform, we detected increased expression of CD9 and CD81 in glioblastoma and low-grade glioma, proposing an upregulation of both tetraspanins early in the tumorigenesis of gliomas." (PMID 36203458, 2022). "The CCK8 assay indicated that knocking down CD81 significantly inhibited glioblastoma cell proliferation." (PMID 35936722, 2022). "Based on these observations, we concluded that specific proteins on extracellular vesicles such as CD9 and CD81 are excellent markers to monitor behavior of glioblastoma cells." (PMID 36203458, 2022). "The Western blot analysis of SOX10 and Nanog in NC-treated and Si-CD81-treated U118 cells indicated that knocking down CD81 weakened the stemness of glioblastoma cells." (PMID 35936722, 2022). "Despite many unresolved questions that we were not able to address so far, our data suggest the changed release of CD9 and CD81-positive EVs by glioblastoma as marker to monitor glioblastoma response to radiotherapy." (PMID 36203458, 2022). "We further found that total counts of double positive FASN+/CD63+ as well as FASN+/CD81+ EVs were significantly increased in the blood of glioblastoma patients, and the former was also significant in patients with anaplastic astrocytomas." (PMID 32178271, 2020). "Several studies have previously reported frequent epigenetic disruption of CD81 in glioblastoma, supporting its tumor-suppressor roles in this cancer type." (PMID 24650279, 2014). "Finally, silencing CD81 in vitro significantly suppressed proliferation, stemness, and migration and facilitated apoptosis in glioblastoma cells." (PMID 35936722, 2022).
glioblastoma (continued). "In glioblastoma, increased CD9 expression was associated with maintenance of glioblastoma stem-like cells, while CD81 was associated with enhanced resistance to radiotherapy by promoting nuclear translocation of RAD51, a protein involved in detection and repair of DNA double strand breaks." (PMID 36203458, 2022). "First, qRT-PCR confirmed that glioblastoma cells express higher CD81 levels than astrocytes." (PMID 35936722, 2022). "Therefore, we analyzed CD9 and CD81-positive EVs in the supernatant of glioblastoma cells 72 h after irradiation with photons or high LET protons, and compared the results to respective non-irradiated controls." (PMID 36203458, 2022). "Moreover, in patients with glioblastoma, high CD81 expression correlated with shorter survival, while, in patients with low-grade glioma, high CD9 expression correlated with shorter survival." (PMID 36203458, 2022). "Finally, we performed quantitative reverse transcription-polymerase chain reaction, cell counting kit-8, cell stemness detection, cell migration, and apoptosis detection in vitro assays to determine the biological role of CD81 in glioblastoma cells." (PMID 35936722, 2022). "Moreover, we detected CD9 and CD81-positive EVs in the supernatant of all glioblastoma cells, although at different concentrations." (PMID 36203458, 2022). "CD81 is highly expressed in glioblastoma (GBM) as a transmembrane protein." (PMID 33919192, 2021). "Tetraspanin markers are commonly used to identify EVs and we previously demonstrated that the number and proportion of CD63+ circulating plasma EVs is significantly elevated in patients with glioblastomas and anaplastic astrocytomas, with a similar trend for CD81+ EVs." (PMID 32178271, 2020). "The CD81 gene showed promoter methylation in 46.1% of tested glioblastomas in the current study." (PMID 22672670, 2012). "Recent glioblastoma methylome studies have shown CD81 methylation rate of 54%." (PMID 22672670, 2012). "That way, CD81 might indirectly affect the therapeutic response of glioblastoma cells." (PMID 36203458, 2022). "Additionally, an existing study has shown the role of CD81 in mediating radioresistance in glioblastoma cells, and our study may form a good complement to this study." (PMID 35936722, 2022). "Finally, in vitro assays revealed the biological role of CD81 in glioblastoma cells." (PMID 35936722, 2022). "To analyze the importance of CD9 and CD81 expression for patients with glioma, we compared gene expression of both tetraspanin genes in glioblastoma (GBM." (PMID 36203458, 2022). "It has been suggested that in glioblastoma, highly methylated genes, such as CD81 (CD81 antigen), DR4 (death receptor 4, TRAIL receptor 1) and GATA6 (GATA binding protein 6), participating in cell adhesion, apoptosis, and proliferation could be important in gliomagenesis." (PMID 22672670, 2012). "Significant results were also observed for TNC+/CD81+ in newly diagnosed and relapsed patients (FC =5.9 and 6.4, respectively), as well as for TNC+/CD63+ (FC = 10.96 in newly diagnosed glioblastoma; p < 0.001)." (PMID 40056466, 2025). "Glioblastoma patients exhibited significant upregulation of CD29, CD44, CD81, CD146, CqQA, and histone H3 compared to healthy volunteers, with additional upregulation of C1QA, CD44, and histone H3 observed to those with stable disease." (PMID 41373835, 2025). "Although OGFOD1, C1RL, CD81, and ITPKC play pivotal roles in several cancers, their involvement in glioblastoma remains undocumented." (PMID 35936722, 2022). "A recent publication described in this context glioblastoma-derived EVs containing CD9 and CD81 in blood samples." (PMID 36203458, 2022). "They applied the designed assay to detect glioblastoma biomarkers CD-pan (CD9, CD63, and CD81), with EGFR, EGFRvIII and GAPDH as control markers, from supernatants of glioblastoma cells." (PMID 33276535, 2020).
glioblastoma (continued). "This is quite relevant to the field of EGFR research, as both EGFR and its glioblastoma mutant EGFRvIII can be found on Flotillin1+ sEVs extracted from the blood of glioblastoma and ovarian cancer patients, as well as on CD9+/CD81+ sEVs." (PMID 33302515, 2020). "The methylation status of MGMT, CD81, GATA6, DR4, and CASP8 in 76 patients with primary glioblastomas was investigated." (PMID 22672670, 2012). "In glioblastoma specimens gene methylation was observed as follows: MGMT in 51.3%, GATA6 in 68.4%, CD81 in 46.1%, DR4 in 41.3% and CASP8 in 56.8% of tumors." (PMID 22672670, 2012). "For CD9, its study in glioblastoma multiforme (GBM) revealed that the increase of CD9 and CD81 in extracellular vesicles (EVs) after radiotherapy was closely related to the cytotoxic response after treatment, which provided a new biomarker for radiotherapy monitoring." (PMID 40530955, 2025). "We therefore concluded that the changed secretion of CD9 and CD81-positive EVs can be used to monitor glioblastoma cell response to radiotherapy irrespective of the radiation technique." (PMID 36203458, 2022). "Since we barely detected CD63-positive sEVs in supernatants of our glioblastoma cells in preliminary experiments, we focused our examinations on the expression of CD9 and CD81 in human glioma tissues using accessible online data and in the different glioblastoma cells." (PMID 36203458, 2022). "The number of CD9 or CD81-positive vesicles in supernatant of non-irradiated glioblastoma did not correlate with radiation-induced cytotoxicity in long-term or short-term assays." (PMID 36203458, 2022). "Our experiments indicate that the amount of secreted CD9 or CD81-positive EVs did not correlate with the tetraspanin levels in glioblastoma cells." (PMID 36203458, 2022). "It further showed that only the total number of CD63+ EVs but not CD81+ EVs was increased in patients with glioblastomas and malignant astrocytomas." (PMID 32178271, 2020). "We detected varying concentrations of CD9 or CD81-positive EVs in the supernatant of different glioblastoma cell lines, but could not use this data to predict the response to radiotherapy." (PMID 36203458, 2022). "Another limitation of our study was that we did not have enough energy and layout to examine the effect of CD81 knockdown on immune regulation of glioblastoma, which may provide inspiration for further studies." (PMID 35936722, 2022). "Since CD81 resides inside the cell membrane of unstimulated microglia, and CLEC12A is expressed at relatively low levels in monocytes, we chose F11R and SELL as representative differentially-expressed flow cytometry markers to study monocyte infiltration in murine glioblastoma." (PMID 24147027, 2013). "Importantly, however, the total count of double positive FASN+/CD63+ EVs (mean 4.1 × 105/mL GBM vs 5.8 × 104/mL HD, P = 0.001) as well as the total count of FASN+/CD81+ EVs (mean 8.0 × 105/mL GBM vs 2.3 × 105/mL HD, P = 0.007) was significantly increased in the plasma of glioblastoma patients." (PMID 32178271, 2020). "Gene expression of both marker was significantly elevated in GBM as well as LGG samples compared to non-malignant samples, suggesting that expression on CD9 and CD81 was elevated early during cancer progression to glioblastoma." (PMID 36203458, 2022).
malaria (15 papers, 2008 to 2025). Malaria is a serious and sometimes fatal disease caused by a parasite that commonly infects a certain type of mosquito which feeds on humans. "Here we show that the two main species causing malaria in humans, Plasmodium falciparum and Plasmodium vivax, rely on two distinct host cell surface proteins, CD81 and the Scavenger Receptor BI (SR-BI), respectively, to infect hepatocytes." (PMID 28506360, 2017). "Nonetheless, complete development of P. berghei EEFs in this model may be attributable to the expression of Scarb1, Met, Cd81, Hgfr, and Prkcz; host genes previously implicated in malaria LS infection." (PMID 32442532, 2020). "For the first time, we also explored the role of CD81 and SR-BI during hepatocyte infection by P. vivax, a widely distributed yet highly neglected cause of malaria in humans, for which the contribution of hepatocyte surface receptors has not been investigated to date." (PMID 28506360, 2017). "Using a mouse model of malaria, we show that CD81 GalNAc-siRNA blocked parasite liver infection in a dose-dependent manner and prevented the onset of blood stage infection." (PMID 40677836, 2025). "When performing EFS analysis for the discrimination between malaria and the severely ill malaria patients, CD81 (0.59) and CD106 (0.36) were the best markers for discrimination according to their normalized ensemble importance." (PMID 36961624, 2023). "Based on ROC analyses, CD106, CD81, osteopontin, and HLA-DR are best-suited for discrimination between malaria and healthy controls based on their high AUC values (> 0.92)." (PMID 36961624, 2023). "More generally, this property of cholesterol to modulate the mode of action of tetraspanins not only affects protein transport [e.g., CD81:CD19; CD9:MHCII], but also malaria or cytomegalovirus infection [through CD81], and cell migration as described later." (PMID 32411706, 2020). "imHCs expressed all major malaria sporozoite-associated receptors known to be essential for parasite entry and intracellular development in the liver, including TAPA-1 (CD81), EphA2 and SR-BI." (PMID 29370800, 2018). "CD81 and EphA2 were expressed at higher levels in imHCs than in HC-04 cells, a cell line most commonly used for malaria sporozoite infection." (PMID 29370800, 2018). "Hepatitis C virus (HCV) and the malaria parasite Plasmodium use the membrane protein CD81 to invade human liver cells." (PMID 30024968, 2018). "Our data confirms that HCV and the malaria parasite Plasmodium use distinct CD81-mediated entry pathways for liver cell invasion." (PMID 30024968, 2018). "CD81 is required for invasion of hepatocytes by sporozoites of human malaria Plasmodium falciparum and rodent malaria Plasmodium yoelii parasites." (PMID 19476617, 2009). "Using the rodent malaria parasite P. yoelii, which also requires CD81 for hepatocyte infection, we showed that a single high dose or a fractional multi-dose siRNA injection was highly effective in preventing liver infection and, thereby, the parasites transition to pathogenic blood stage infection." (PMID 40677836, 2025). "Moreover, the sEV surface proteins showed trends for gradual up- (CD81) or down-regulation (HLA-DR) with more severe laboratory alterations in malaria patients." (PMID 36961624, 2023). "CD81 is highly expressed on monocyte-derived EVs and was induced in malaria samples." (PMID 36961624, 2023). "As malaria plasma samples contained more CD81+ sEVs, along with reduced HLA-DR levels, the amount of monocyte-derived EVs might increase during malaria." (PMID 36961624, 2023). "The signal intensities for capturing sEVs with the antibody cocktail against CD9, CD63, and CD81 and detecting them with unspecific IgG antibodies were similar in the two groups, indicating that the total amounts of released sEVs between malaria and healthy controls were comparable." (PMID 36961624, 2023).
malaria (continued). "Notably, CD81 promotes invasion of the malaria sporozoites from Plasmodium yoelii and Plasmodium falciparum via a cholesterol-dependent mechanism." (PMID 35612284, 2022). "Next we set out to understand whether a similar or distinct set of CD81 PPIs was necessary for hepatoma cell entry of the malaria parasite Plasmodium yoelii." (PMID 30024968, 2018). "CD81, a protein of the tetraspanin superfamily, is the only hepatocyte surface protein that has been shown to be strictly required for the infection by the malaria parasite." (PMID 18389082, 2008). "The interaction between CD81 and CD9P-1 could also be exploited in the field of parasitic pathologies, because it has been shown that binding to and regulation of CD81 function by CD9P-1 represents a negative regulator of infection by Plasmodium yoelii (a malaria pathogen in rodent species)." (PMID 37046846, 2023). "We found that, in contrary to P. falciparum, antibodies against SR-BI but not against CD81 inhibit infection of primary human hepatocyte cultures by P. vivax sporozoites, illustrating that the two main species causing malaria in humans use distinct routes to infect hepatocytes." (PMID 28506360, 2017). "The selected features for the discrimination between healthy and malaria were CD106, CD81, Osteopontin, HLA-DR and HBEGF on plasma sEVs together with the concentration of thrombocytes." (PMID 36961624, 2023). "Here, the selected features were thrombocytes, CD106, Osteopontin, CD81, HLA-DR and HBEGF for discrimination between healthy and malaria." (PMID 36961624, 2023). "CD81 and CD9 were more abundant on plasma sEVs of malaria patients in comparison to healthy controls, while all other 14 proteins were significantly less abundant." (PMID 36961624, 2023). "Our study maps the liver cell interactome of CD81 and provides new insight into the distinct cell invasion mechanisms of HCV and malaria parasites." (PMID 30024968, 2018). "CD81 is a cell membrane protein, which functions as entry factor for hepatitis C virus (HCV) and malaria sporozoites in the human liver." (PMID 30024968, 2018). "Moreover, this lipid transport function has been demonstrated to modulate the role of CD81 in HCV and malaria entry." (PMID 32900848, 2020). "Currently, it remains enigmatic how CD81 guides the entry process of both pathogens and whether it functions in a similar way during liver cell invasion of HCV and malaria parasites." (PMID 30024968, 2018). "We therefore predict that if a CD81 partner interacting through the A–B junction is shown to play a key role during the infection by malaria sporozoites, it will not play a crucial role during HCV infection." (PMID 18389082, 2008). "Additional ensemble feature selection revealed CD106, Osteopontin, CD81, major histocompatibility complex class II DR (HLA-DR), and heparin binding EGF like growth factor (HBEGF) together with thrombocytes to be a feature panel for discrimination between healthy and malaria." (PMID 36961624, 2023). "In this study, we found that the surface proteome of plasma sEVs differs in patients with malaria compared to healthy controls and that thrombocyte levels together with CD106, Osteopontin, CD81, HLA-DR and HBEGF might serve as a feature panel for donor discrimination." (PMID 36961624, 2023). "Intriguingly, the rodent malaria parasite P. berghei can infect cells lacking CD81, however the molecular basis of this alternative entry pathway was until now totally unknown." (PMID 28506360, 2017).